LCE1D (late cornified envelope 1D)
Description:
Precursors of the cornified envelope of the stratum corneum.
Synonyms: LEP4
Tractability: Antibody: its Gene Ontology location is reachable by antibodies, with high confidence.
Gene: Protein-coding gene on chromosome 1 (152,796,721 to 152,798,181, forward strand). Ensembl gene ENSG00000172155.
Pathways (Reactome):
Developmental Biology: Formation of the cornified envelope
Gene Ontology:
Molecular function: identical protein binding; protein binding
Biological process: cellular response to calcium ion; cognition; epidermis development
Cellular component: cornified envelope; cytoplasm; perinuclear region of cytoplasm
Genetic constraint (gnomAD): Loss-of-function variants: 4 observed, 3.65 expected, observed/expected ratio (o/e) 1.1, 90% interval 0.51 to 1.87. That is too few expected variants to judge how well the gene tolerates losing a copy. Missense variants: 86 observed, 118.26 expected, observed/expected ratio (o/e) 0.73, 90% interval 0.61 to 0.87. Synonymous variants: 44 observed, 45.12 expected, observed/expected ratio (o/e) 0.98, 90% interval 0.76 to 1.25.
Homologues: Paralogues in human: LCE1E (94% identical), LCE1F (91% identical), LCE2D (71% identical), LCE2C (70% identical), LCE2B (69% identical), LCE2A (68% identical), LCE5A (67% identical), LCE3B (46% identical), LCE3C (46% identical), LCE3D (46% identical), LCE3A (45% identical), LCE3E (45% identical), and 8 more.
Diseases named in the same sentence as LCE1D in open-access papers:
LCE1D is named in the same sentence as 1 disease in open-access papers, as found by Europe PMC text mining. Sharing a sentence is not in itself a finding about the gene and the disease.
LCE1D shares sentences with these, for which no sentence is quoted: tumor (1 paper).